CYP24A1 (cytochrome P450 family 24 subfamily A member 1)
Diseases named in the same sentence as CYP24A1 in open-access papers (continued):
Sharing a sentence is not in itself a finding about the gene and the disease.
tumor (continued). "Tumor tissues from VD3-deficient patients exhibited lower levels of β-catenin and TGFβ1, along with higher levels of CYP24A1 compared to VD3-normal patients." (PMID 38360633, 2024). "COX-2 expression in tumor tissue was notably higher in tumors with high expression of CYP24A1, and this difference was statistically significant when considering all patients." (PMID 38355711, 2024). "The results showed that compared to the oe-NC group, the tumor metastatic nodules in the lungs of the oe-CYP24A1 and oe-TFPI2 groups were significantly reduced." (PMID 39068476, 2024). "The results showed that compared with the oe-NC group, the tumor volume and weight in the oe-CYP24A1 group and the oe-TFPI2 group were significantly reduced." (PMID 39068476, 2024). "When the tumor is poorly differentiated, expression of CYP24A1 is increased and that of CYP27B1 is reduced." (PMID 36986255, 2023). "It was also reported that increased regulation of the vitamin D synthesis gene CYP2R1 and CYP27B1 and vitamin D metabolic genes CYP24A1 leading to changes in vitamin D bioavailability and anti-tumor activity, then influence the development of cancer." (PMID 37644572, 2023). "For example, it is feasible that tumour cells express less CYP24A1 as a result of a dysregulated and low VDR expression." (PMID 36362766, 2022). "In breast tissues, it has been shown that with tumor progression, there was an increase in 1,25(OH)2D 24-hydroxylase (CYP24A1) expression and a decrease in CYP27B1 expression." (PMID 35743729, 2022). "Poorly differentiated tumours demonstrated a similar CYP24A1 protein expression compared to well differentiated cancers." (PMID 36362766, 2022). "When the CYP24A1 was deleted in the BrafV600E tumor mice model, the growth of tumors was attenuated significantly." (PMID 36527000, 2022). "When the tumor is poorly differentiated, there is greater expression of CYP24A1 and reduced expression of CYP27B1." (PMID 34836039, 2021). "Based on the data from the TCGA COAD program, we found that KIF5B and CYP24A1 were significantly overexpressed in tumor samples compared to normal tissues." (PMID 33791222, 2021). "CYP24A1 was found to produce bioactive tumor-suppressive vitamin D metabolites (i.e., 20,24(OH)2D and 20,25(OH)2D) rather than degrading 1,25(OH)2D3." (PMID 34208589, 2021). "Clearly, VDR activation in tumors requires ligand, which depends on the patient's overall vitamin D status as well as the relative activity of CYP27B1 and CYP24A1 within individual tumor cells." (PMID 34950835, 2021). "They found that elevated protein levels of CYP24A1 induced deeper tumour invasion, lymph node metastases and venous permeation." (PMID 32679655, 2020). "High local expression of CYP24A1 is predicted to limit tumor exposure to 1,25(OH)2D3, restricting its efficacy." (PMID 32183160, 2020). "We then showed that the activation of SIRT6 by MDL-811 suppressed the transcription of CYP24A1, which synergistically enhanced the anti-tumor effect of vitamin D3 (VD3) in CRC." (PMID 32483423, 2020). "Knockdown of CYP24A1 significantly decreased cell proliferation resulted in tumor growth delay and smaller tumor size with decreased RAS protein level, thus reducing phosphorylated AKT." (PMID 32998690, 2020). "In our ongoing investigations, we are looking to delineate the role of tumor CYP24A1 expression and activity in genotype- and therapy-specific responses to vitamin D." (PMID 32183160, 2020). "Preclinical studies revealed that CYP24A1 inhibitors can suppress the breakdown of 1,25D3 in tumor cells and enhance the anti -tumor effects of 1,25D3 on cell growth and gene expression." (PMID 29449867, 2018). "There is evidence that a high level of CYP24A1 and/or other factors that limit tumor levels of 1,25D(OH)2D3 can prevent VDR mediated growth inhibition." (PMID 28591703, 2017). "We observed increased tumour aggressiveness and larger tumours in CYP24A1‐overexpressing xenografts compared with controls." (PMID 26238339, 2016).
tumor (continued). "Studies reported that the major vitamin D catabolizing enzyme, CYP24A1 (24-hydroxylase), is often amplified and overexpressed in tumor cells." (PMID 27635343, 2016). "Combination of dietary vitamin D and soy increases volume and weight of tumours overexpressing CYP24A1." (PMID 26238339, 2016). "Combining all diet groups, the tumours overexpressing CYP24A1 were significantly larger (p < 0.001) and heavier (p < 0.001)." (PMID 26238339, 2016). "To determine causality between CYP24A1 and tumour growth, we established xenografts in male SCID mice with HT29 cells stably overexpressing either GFP‐tagged CYP24A1 or GFP." (PMID 26238339, 2016). "CYP24A1 overexpression increased tumour weight when compared with the HT29GFP xenografts, except in the mice receiving low vitamin D diet without soy." (PMID 26238339, 2016). "Soy reduced tumour volume only in the control xenografts, while the tumours overexpressing CYP24A1 were larger in the presence of dietary soy." (PMID 26238339, 2016). "Significance was reached only between CYP24A1 overexpressing tumours vs. HT29GFP xenografts receiving high vitamin D with soy." (PMID 26238339, 2016). "CYP24A1 overexpression is observed in various solid tumours, 18, 28, 29, 30, 31 indicating a selection advantage for tumour cells with high CYP24A1 expression." (PMID 26238339, 2016). "Analysing the effect of the diet and CYP24A1 level on tumour volume, we observed that in general, CYP24A1 overexpression (black lines) increased tumour volume when compared with the HT29GFP xenografts (grey lines), independent of diet." (PMID 26238339, 2016). "CYP27B1 and CYP24A1 expression were significantly different between tumor and normal tissues in NSCLC." (PMID 25544771, 2015). "Based on the understandings, we performed RT-qPCR to assess the expression of CYP27B1 and CYP24A1 in lung tumor and non-tumor tissues." (PMID 25544771, 2015). "Despite the general decrease in CYP24A1 mRNA in tumor specimens compared to the surgical margin, we found increased expression in higher (Stage I to III, UICC grading 1 to 3) developed tumors (rs=0.36; P<0.05, Spearman's test, P=0.001; Kruskal-Wallis ANOVA)." (PMID 26260259, 2015). "The highest expression of CYP24A1 was observed in surgical margin specimens in comparison to both tumor and control samples (P<0.0001)." (PMID 26260259, 2015). "A correlation between tumor progression and CYP24A1 expression at the mRNA level was observed in the CRC biopsies." (PMID 26260259, 2015). "Compared to non-tumor tissues, CYP27B1 mRNA expression was significantly lower in tumor tissues (p<0.001), and the expression of CYP24A1 was significantly higher in tumor than in non-tumor tissues (p<0.001)." (PMID 25544771, 2015). "In a study of prostate cancer, changes in the epigenetic patterns of endothelial cells in the tumor microenvironment showed that methylation of the promoter of the gene CYP24A1 plays a role in determining the phenotype of the tumor-associated vasculature." (PMID 26000021, 2015). "To examine if the SNPs in CYP27B1 and CYP24A1 affect their mRNA expression, we compared levels of mRNA expression by the genotypes of CYP27B1 and CYP24A1 in 153 tumor samples." (PMID 25544771, 2015). "Theoretically, elevated levels of CYP24A1 should stimulate degradation of 1,25(OH)2D3 with attenuation of its antitumorigenic actions, enabling tumor growth or progression." (PMID 25334067, 2014). "In PDAC patients, the tumor expressed significantly more CYP24A1 than the acini, endocrine islets, or stroma." (PMID 25090635, 2014). "In the endocrine cells of PDAC patients, CYP24A1 expression was significantly lower than in the patients with CP (and probably in the normal pancreas), while it was increased in the tumor cells." (PMID 25090635, 2014). "Since cyp24a1 has been proposed to play a critical role in the development of resistances to tumor therapeutic application of vitamin D3, we aimed at further characterizing the translational regulation of cyp24a1." (PMID 24416388, 2014).
tumor (continued). "Of these, CYP24A1 was induced over 7-fold and was validated in another set of tumor samples, clearly indicating activation of VDR signaling." (PMID 24982636, 2014). "Spearman's correlation analysis showed significant correlation between CYP24A1 and Ki67 in the tumor and stroma of the PDAC patients." (PMID 25090635, 2014). "Further studies are required to elucidate the functional consequences of altered cyp24a1 translation but also to determine changes in cyp24a1 translation in other tumor models." (PMID 24416388, 2014). "In five independently-derived primary cultures of cancer-associated fibroblasts, CYP24A1 expression was consistently induced in response to 1,25(OH)2D3 0.5nM indicating active VDR signaling in the tumor stroma." (PMID 23497279, 2013). "We have previously shown that epigenetic silencing of CYP24A1 in TdECs from a mouse syngeneic tumor model contributes to selective growth inhibition by calcitriol." (PMID 23978847, 2013). "The findings suggest that CYP24A1 overexpression is likely to deplete tumor calcitriol (1,25-dihydroxyvitamin D3) levels, possibly increasing the proliferative potential of the tumors." (PMID 23463632, 2013). "Factor 4TU reflects a strong positive correlation between CYP24A1 and histopathological tumor grading." (PMID 24213465, 2012). "In contrast, CYP24A1 is augmented more than 2.5 fold in invasive tumours (53.7%), compared with benign breast lesions (19.0%) and this difference is also significant (p < 0.0001)." (PMID 20831823, 2010). "Concerning CYP27B1 expression, we have encountered positive staining in 66.4% of the cases (91 out of 137 samples); whereas CYP24A1 expression was observed in 56.0% of the tumours (70 out of 125 cases)." (PMID 20831823, 2010). "Regarding CYP27B1 expression, 44.6% of cases were positive (123 out of 276 samples), whereas 53.7% of cases (151 out of 281 tumours) presented positivity for CYP24A1." (PMID 20831823, 2010). "Recent studies have shown that CYP24A1 plays an important role in the development and progression of many cancers, and abnormalities in its expression level are closely related to the biological behavior of tumor." (PMID 40630116, 2025). "Targeting circ-CYP24A1 in exosomes significantly reduced tumorigenic behaviors, underscoring its potential as a non-invasive biomarker for cSCC diagnosis and a novel therapeutic target for limiting tumor progression." (PMID 40303340, 2025). "The REG4 antibody that we tested strongly stained tumor‐associated neutrophils, and the CYP24A1 antibody gave weak or no staining, leading to the exclusion of these markers." (PMID 39935174, 2025). "A significant difference in promoter methylation level of CYP24A1, which was quantified by averaging the methylation levels of all three significant CpG sites, was observed between tumor tissues and adjacent normal tissues in both GSE48684 and GSE193535 datasets (p < 0.05)." (PMID 39858498, 2025). "Interestingly, studies have revealed that inhibiting or knocking down CYP24A1 significantly impedes tumor growth, whereas overexpressing CYP24A1 promotes tumor progression and metastasis." (PMID 40362248, 2025). "Acquired gefitinib-resistant NSCLCs upregulate their own VDR protein expression, which may induce CYP24A1 production and accelerate the catabolism of 1,25(OH)2D3, thereby suppressing the anti-tumor effects of 1,25(OH)2D3." (PMID 40872626, 2025). "However, a more in-depth analysis of CYP24A1 expression in various pancreatic cell types revealed that during tumor transformation, the expression of CYP24A1 is lost in untransformed endocrine cells, while it drastically increases in transformed ductal cells." (PMID 38732007, 2024). "Therefore, along with inhibiting angiogenesis and regressing existing immature capillaries, 1,25-D treatment produces effects in tumor cells similar to those of epigenetic silencing of CYP24A1." (PMID 38846332, 2024). "A correlation between the tumor’s clinical characteristics and circ-CYP24A1 was also reported." (PMID 38473864, 2024).
tumor (continued). "However, the enzyme CYP24A1 or 24-hydroxylase, which degraded 1,25(OH)2D3 to inactive calcitroic acid, was reported upregulated in tumor cells or other cells." (PMID 36776613, 2023). "Furthermore, there are studies that relate increased expression of CYP24A1 to a worse prognosis, since it has been observed that when the tumor is poorly differentiated, gene expression is greater." (PMID 36986255, 2023). "In addition, there is evidence that vitamin D catabolism via 24-hydroxylase (CYP24A1) is altered in tumour cells, thus, reducing local active vitamin D levels in cancer cells." (PMID 36362766, 2022). "Therefore, it can be concluded that depletion of CYP24A1 profoundly inhibited the cancer cell proliferation and affected the suppression effect of calcitriol on tumor growth." (PMID 36527000, 2022). "Interestingly, studies suggest that CYP24A1 is increased in malignant tumour cells compared to healthy tissue, leading to an enhanced 1,25(OH)2D3 de-activation." (PMID 36362766, 2022). "They found that this phenotype was associated with the repression of the MAPK, PI3K/Akt, and TGFβ signaling pathways, and a loss of EMT in CYP24A1 knockout cells was also associated with the downregulation of genes involved in EMT, tumor invasion, and metastasis." (PMID 34422647, 2021). "Unbalanced, high basal levels of CYP24A1, however, may promote the progression of tumor growth, even in the colon." (PMID 32422882, 2020). "Interestingly, CYP24A1 is upregulated in tumor cells to abrogate the vitamin D–related anti-tumor effects." (PMID 32582151, 2020). "However, the level of CYP24A1 was the highest in 4T1 tumor tissue from the same treatment group (100 IU+cal), and with the low level of CYP2R1 protein in these mice we observed the lowest plasma level of 25(OH)D3." (PMID 33172201, 2020). "If there is a causal link between CYP24A1 expression and tumour proliferation, tumours overexpressing CYP24A1 would grow faster and a selective inhibition of CYP24A1 in the tumour combined with increased vitamin D supplementation could reduce tumour growth." (PMID 26238339, 2016). "This increase was higher in mice bearing CYP24A1‐overexpressing tumours (p < 0.001)." (PMID 26238339, 2016). "Irrespective of the dietary vitamin D3, dietary soy is able to increase tumour volume when tumours overexpress CYP24A1, suggesting that combination of vitamin D3 and soy could have an anti‐tumourigenic effect only if CYP24A1 levels are normal." (PMID 26238339, 2016). "Finally, CYP24A1 expression in tumor tissue was correlated with VDR mRNA levels (rs=0.57, P<0.05; Spearman's test)." (PMID 26260259, 2015). "Levels of CYP27B1 and CYP24A1 expression in tumor tissues were analyzed in 153 NSCLC patients." (PMID 25544771, 2015). "Interestingly, in PDAC patients, the tumor cells expressed more CYP24A1 than any other cell type, even more than the endocrine cells." (PMID 25090635, 2014). "However, this correlation is lost in PDAC patients where VDR protein levels are highest in the endocrine cells while the CYP24A1 is highest in tumor cells." (PMID 25090635, 2014). "Additionally, in the tumor itself, the high CYP24A1 levels would catabolize 1,25(OH)2D3 immediately, impairing its anti-tumorigenic effects." (PMID 25090635, 2014). "Moreover, the 1,25 D3 catabolic enzyme Cyp24 (also known as Cyp24A1) was induced in macrophages when they were co-cultured with tumor cells." (PMID 23424670, 2013). "Notably, CYP24A1 mRNA in low grade and high grade lesions was approximately 20, respectively 35 times higher (p < 0.001) than in paired specimens of tumor-adjacent mucosa." (PMID 24213465, 2012). "Likewise, the clusters built at a somewhat higher distance from age and gender or from CYP24A1 and tumor grading reflect Factors 3TU and 4TU, respectively." (PMID 24213465, 2012). "In cancer, the expression of CYP24A1 decreases as a function of tumour cell dedifferentiation." (PMID 20831823, 2010).